STAT3 (signal transducer and activator of transcription 3)
Diseases named in the same sentence as STAT3 in open-access papers (continued):
Sharing a sentence is not in itself a finding about the gene and the disease.
autoimmune disease (continued). "STAT3 (signal transducer and activator of transcription 3) is known to be an important regulator of inflammation, protease activation, and apoptosis processes which are involved in the pathogenesis of COPD and other autoimmune diseases like cancer or skeletal muscle function and disorders." (PMID 34815425, 2021). "STAT3 in CD4+ T cells was the top predicted transcription factor common for both resulting lists (Supplementary Datas 6, 7) and thus may regulate the pathogenicity of human TH17 cells in autoimmune diseases." (PMID 29150604, 2017). "Interestingly, IL-10R signaling and downstream STAT3 phosphorylation are defective in CD4+ T cells from patients with systemic lupus erythematosus and MS, suggesting that failure of T cell suppression by IL-10 may play an important role in autoimmune disease, including in the CNS." (PMID 32303238, 2020). "We previously tested whether genes coregulated by the “Th17 core” (RORC, STAT3, BATF, IRF4, and MAF) were enriched for gene sets from GWAS of nine autoimmune diseases and three “negative controls” (Alzheimer's, schizophrenia, and type 2 diabetes)." (PMID 30696696, 2019).
pulmonary fibrosis (148 papers, 2010 to 2026). Chronic progressive interstitial lung disorder characterized by the replacement of the lung tissue by connective tissue, leading to progressive dyspnea, respiratory failure, or right heart failure. "Abnormal activation or suppression of STAT3 is closely linked to the pathogenesis and progression of several pulmonary disorders, such as pulmonary fibrosis, pulmonary infections, and chronic obstructive pulmonary disease." (PMID 40969747, 2025). "Several reports have demonstrated that STAT3 activation can promote and sustain COVID‐19‐associated hyperinflammatory syndrome, thrombosis, lymphopenia and lung fibrosis." (PMID 38501860, 2024). "Next, we observed that the overexpression of STAT3 or the suppression of miR-15b-5p restored lung fibrosis and injury inhibited by Rg1 in T2DM-associated PTB mice." (PMID 36248428, 2022). "The overexpression of STAT3 or the suppression of miR-15b-5p restored lung fibrosis and injury inhibited by Rg1 in T2DM-associated PTB mice." (PMID 36248428, 2022). "Further experiments shown that miR-125a-3p inhibits Fyn expression causing the inactivation of Fyn downstream effector Stat3 and attenuating pulmonary fibrosis." (PMID 32565740, 2020). "Hyperelevated activation of STAT-3 in a genetic mouse model system has also recently been shown to render animals highly susceptible to fibrosis in the bleomycin model of lung fibrosis, whereas hypoactivation of STAT3 rendered these mice protected." (PMID 24381786, 2013). "We therefore mimicked this situation by testing the susceptibility of Stat3+/− mice to bleomycin-induced lung fibrosis." (PMID 22684844, 2012). "Studies on A. cantonensis in rats have shown that IL-6 upregulation was associated with persistent pneumonia in early infection and lung fibrosis in later stages, mediated through the IL-6/Stat3 pathway, which enhances inflammatory processes and leads to structural damage in lung tissue." (PMID 40529303, 2025). "To identify factors that may modulate STAT3 expression during lung fibrosis, we interrogated ChIP-seq datasets in the ENCODE 3 repository." (PMID 36899902, 2023). "The authors observe that the circulating monocyte/macrophage phenotype could contrast with macrophage signature in tissues such as lung, in which a STAT3-dependent expression of CD163 was associated with pulmonary fibrosis." (PMID 30249259, 2018). "However, the individual mechanisms by which JAK2 and STAT3 cause pulmonary fibrosis are currently unknown, and together with the mechanism underlying the synergistic effects of dual inhibition, remain to be determined in future research." (PMID 29409529, 2018). "For example, siRNA targeting the STAT3 signaling pathway has shown therapeutic efficacy in both idiopathic pulmonary fibrosis and lung metastatic osteosarcoma." (PMID 41480009, 2026). "In contrast, in pulmonary fibrosis, STAT3 directly recruits H3K27ac‐modified histones to super enhancer (SE) loci." (PMID 40464702, 2025). "Most of the significantly enriched TFs related to pulmonary fibrosis included STAT3, FOXP1, JUNB, ATF3, FosL2, BATF, Fra2 and AP‐1." (PMID 40464702, 2025). "In recent years, different compounds have been reported to improve pulmonary fibrosis by inhibiting the phosphorylation of STAT3." (PMID 41155944, 2025). "The pathological activation of lung fibroblasts in COVID-19 patients involved intrinsic PDLIM2 repression, Because the NF-κB, STAT3, cellular stress, pulmonary fibrosis, pathogen-induced cytokine storm." (PMID 41000764, 2025). "Another study suggested that inhibition of ROCK ameliorates pulmonary fibrosis by suppressing M2 macrophage polarization through the phosphorylation of STAT3." (PMID 40170095, 2025). "JAK2/STAT3 is an important advocate of inflammation and fibrosis pathways, and inhibition of JAK2/STAT3 can reduce alveolar inflammation and pulmonary fibrosis in IPF patients." (PMID 41155944, 2025).
pulmonary fibrosis (continued). "In a recent study, a pan-ROCK inhibitor (WXWH0265) suppressed M2 macrophage polarization through inhibition of ROCK activity via down-regulated signal transducer and activator of transcription 3 phosphorylation in the treatment of pulmonary fibrosis." (PMID 38552026, 2024). "Research on pulmonary fibrosis has demonstrated that JAK2/STAT3 signaling pathway activation is critical in inducing epithelial to mesenchymal and fibroblast to myofibroblast transitions." (PMID 38253716, 2024). "The JAK2-induced STAT3 phosphorylation is an especially potent inducer of myofibroblast differentiation in human and mouse pulmonary fibrosis." (PMID 37917219, 2024). "There is substantial evidence that the JAK/STAT3 pathway has a crucial role in many fibrotic diseases, e.g., systemic sclerosis, pulmonary fibrosis, and renal fibrosis." (PMID 37917219, 2024). "By targeting ADAM17, miR-708-3p represses the GATA/STAT3 signalling pathway in idiopathic pulmonary fibrosis (IPF) reducing fibrosis." (PMID 38920689, 2024). "Consistent with the murine model of lung fibrosis, we observed higher levels of STAT3 mRNA and pSTAT3 protein in CD4+ T cells from the male compared to the female sarcoidosis patients." (PMID 36899902, 2023). "IL-11 has been shown to participate in lung fibrosis through STAT3 activation in a BLM-induced fibrosis mouse model." (PMID 37833957, 2023). "We also assessed IL-17A and TGF-β1 production by sex, as CD4+ T cells promote pulmonary fibrosis through the STAT3-medicated production of IL-17A and TGF-β1." (PMID 36899902, 2023). "In contrast to previous findings, our results further supported the involvement of the α7nAChR-mediated JAK2/STAT3 pathway in the differentiation of Th17 cells, revealing a specific action of this pathway in regulating lung fibrosis." (PMID 37064881, 2023). "In this study, MET blocked α-smooth muscle actin (α-SMA) accumulation in vivo accompanied with S100A4 expression and STAT3 phosphorylation inhibition, resulting in attenuating the progression of lung fibrosis after BLM administration." (PMID 36817136, 2023). "We also investigated one of the main inflammatory pathways induced by pulmonary fibrosis such as the JAK2/STAT3 pathway, to evaluate a possible mechanism of action underlying the beneficial effects of KYP-2047 on pulmonary fibrosis." (PMID 37626373, 2023). "In RA-ILD presenting as UIP, Janus kinase 2/signal transducer and activator of transcription 3 (JAK2/STAT3) were identified as intermediary molecules of TGF-β in activating myofibroblasts promoting lung fibrosis." (PMID 36768729, 2023). "Studies have found that EBI3 can alleviates bleomycin-induced pulmonary fibrosis by suppressing DNA enrichment of STAT3." (PMID 37480105, 2023). "Although ESR-1-/- mice and surgical ovariectomy confirm estrogen’s profibrotic capacity in lung fibrosis, it is worth noting that Th17 cell differentiation is reduced due to the transcription factor ERα‘s ability in relation to the STAT3 promoter." (PMID 36899902, 2023). "Estrogen clearly augments the development of lung fibrosis; yet, the binding of ERα to the STAT3 promoter shifts profibrotic cytokine expression away from proinflammatory phenotypes mediated by IL-17A to immunosuppressive phenotypes mediated by TGF-β1." (PMID 36899902, 2023). "Previous studies found that the Janus kinase 2 (JAK2)/signal transducer and activator of transcription 3 (STAT3) signaling pathways are involved in idiopathic pulmonary fibrosis (IPF)." (PMID 35120332, 2022). "Recently it was reported that ASS1 deficiency happened in pulmonary fibrosis, MET can be activated by knocking down ASS1, then interacting with the upstream of the Src-STAT3 signaling to up-regulate the proliferation of fibroblast cells." (PMID 36147332, 2022).
pulmonary fibrosis (continued). "Honokiol can inhibit TGF-β/Smad signaling, matrix proteins, and the IL-6/CD44/STAT3 axis to reduce pulmonary fibrosis, which exerts anti-inflammatory and antioxidant effects." (PMID 36588723, 2022). "Overall, our study implicates the low-diversity gut microbiota as a contributor of pulmonary fibrosis severity through their capacity to activate the IL-6/STAT3/IL-17A signaling pathway." (PMID 36543914, 2022). "A large amount of evidence has shown that Stat3 plays an important role in the occurrence and development of pulmonary fibrosis." (PMID 35172837, 2022). "Signal transducer and activator of transcription 3 (STAT3) activation pathways were involved in lung-fibrosis-driven fibroblast senescence." (PMID 35682743, 2022). "The distinctions in the percentages of CD4 + IL-6+ and CD4 + IL-17A + T cells among mice in different housing cohorts support microbiota-induced alterations to the IL-6/ STAT3/IL-17A pathway in pulmonary fibrosis." (PMID 36543914, 2022). "Exaggerated and prolonged STAT3 activation is a feature of many fibrotic disorders including liver, kidney, and lung fibrosis, as well as a number of cancers." (PMID 33946612, 2021). "Activation of STAT3 participates in fibrosis pathways, leading to lung fibrosis by promoting epithelial damage and fibroblast activation." (PMID 34831433, 2021). "No further reductions in proliferation or protein expression were observed in cells treated with both Stattic and KX-01 plus Stattic, thus suggesting that KX-01 ameliorates experimental pulmonary fibrosis at least in part by inhibiting STAT3 activation." (PMID 34349652, 2021). "Mechanistic study elucidated that AOBEE alleviated pulmonary fibrosis through lnc865- and lnc556-mediated mechanism, in which both lnc865 and lnc556 sponged miR-29b-2-5p to target signal transducer and activator of transcription 3 (STAT3)." (PMID 33929970, 2021). "The JAK2 and STAT3 mRNA transcript levels and protein expression were increased in the isolated pulmonary arteries of idiopathic fibrosis pulmonary (IPF) patients with PH." (PMID 34067108, 2021). "Overall, these findings revealed that KX-01 can alleviate experimental pulmonary fibrosis via suppressing the p-SRC/p-STAT3 signaling pathways." (PMID 34349652, 2021). "In the present study, we found that KX-01 treatment was sufficient to reduce p-SRC and p-STAT3 levels and to thereby alleviate pulmonary fibrosis." (PMID 34349652, 2021). "A previous study in vivo also showed induction of STAT3-mediated Gremlin-1 in lung fibrosis and a recent paper demonstrated that IL-6 trans signaling in idiopathic pulmonary fibroblasts elevated Gremlin-1, which was reduced with tocilizumab." (PMID 34150776, 2021). "Between these, only STAT3 showed a documented involvement in several fibrotic processes, with a role in bleomycin-induced lung fibrosis and idiopathic pulmonary fibrosis (IPF)." (PMID 33804639, 2021). "We previously found that SERCA2a overexpression inhibits IL6/STAT3 signaling in vivo using the bleomycin-induced pulmonary fibrosis model and in vitro in pulmonary fibroblast isolated from healthy donors." (PMID 34502015, 2021). "In conclusion, AOBEE promoted KLF4 degradation leading to the attenuation of pulmonary fibrosis by inhibiting TGFβ1–smad/p38MAPK–lnc865/lnc556–miR-29b-2-5p–STAT3 signal pathway." (PMID 33929970, 2021). "We investigated one of the key inflammatory pathways induced by pulmonary fibrosis: JAK2/STAT3 and Ikb-α/NF-kB systems." (PMID 32660140, 2020). "Studies have shown that STAT family members play an important role in the occurrence and development of pulmonary fibrosis; STAT-3 signaling regulates fibroblasts during the development of pulmonary fibrosis." (PMID 32054021, 2020). "Dual JAK2/STAT3 inhibition was more effective for inhibiting both of these cellular transitions and lung fibrosis than the individual inhibition of JAK2 or STAT3, which implies synergistic and independent roles of these proteins in pulmonary fibrosis." (PMID 32660140, 2020).
pulmonary fibrosis (continued). "The development of pulmonary fibrosis in mice and differentiation of lung fibroblasts to collagen-producing myofibroblasts involves STAT3 activation by TGFß or IL-6 trans-signaling." (PMID 31694340, 2019). "CircRNA‐662 and 949 can function as miR‐29b sponges to regulate STAT3 and Gli2, which are the main regulatory factors of lung fibrosis." (PMID 31448882, 2019). "Gp130 cytokines robustly activate STAT3 cell signaling, and in genetic models in mice, the over-activation of STAT3 renders animals much more sensitive to the ECM remodeling effects in the bleomycin model of lung fibrosis." (PMID 30764496, 2019). "The activity of AKT in lung tissue was suppressed, but conversely, the activity of STAT3 was enhanced during lung fibrosis in mice." (PMID 31049028, 2019). "The cytokine IL-6 functions as a proinflammatory factor as well as a profibrotic factor in pulmonary fibrosis, and the signaling pathway of IL-6/Stat3 has been shown to play an important role in the pathogenesis of lung fibrosis." (PMID 31309122, 2019). "In an intraperitoneal bleomycin lung fibrosis model, we showed that inhibition of STAT3 phosphorylation by C188-9 ameliorated the development of pulmonary fibrosis in mice exposed to bleomycin." (PMID 30081609, 2018). "Genetic or pharmacologic inactivation of SHP2 promotes accumulation of JAK2 phosphorylated at Y570, reduces JAK2/STAT3 signaling, inhibits TGFβ-induced fibroblast activation and ameliorates dermal and pulmonary fibrosis." (PMID 30108215, 2018). "In the current study, the expression level of JAK1, STAT3 and ADAM17 decreased in FFK treatment group compared to BLM treatment group, thus indicating the possible pathways implicated in lung fibrosis as targets of therapeutic attempts." (PMID 30092799, 2018). "In rats administered JSI-124, a Jak2 inhibitor that targets STAT3 indirectly, several markers of bleomycin-induced lung fibrosis were reduced." (PMID 30081609, 2018). "The JAK2/STAT3 pathway is activated in IPF, and treatment with JSI-124 (a dual inhibitor of JAK2/STAT3) decreases collagen deposition during lung fibrosis." (PMID 30524284, 2018). "Dual JAK2/STAT3 inhibition was more effective for inhibiting both these cellular transitions and lung fibrosis than the individual inhibition of JAK2 or STAT3, which implies synergistic and independent roles of these proteins in IPF." (PMID 29409529, 2018). "In our culture system, we found significant activation of STAT3 signaling, supporting previously published data regarding its relevance in pulmonary fibrosis." (PMID 28629363, 2017). "Recently, besides TGF-β/Smad3 signaling, the signaling loop of IL-6/gp130/Stat3 has been shown to play a crucial role in the pathogenesis of lung fibrosis." (PMID 26289430, 2015). "Transcription factor STAT3 is associated with chronic inflammatory diseases and the transcription products of STAT3, such as IL-6, IL-10, and IL-17, are involved in the pathogenesis of pulmonary fibrosis." (PMID 23869224, 2013). "Sustained activation of STAT3 has been suggested to play a critical role in the pathogenesis of lung fibrosis by differentially inducing both apoptotic and proliferative cellular signals." (PMID 23903001, 2013). "STAT3 has recently been suggested to be a central mediator of pulmonary fibrosis via dysregulation of epithelial-mesenchymal communication." (PMID 24058608, 2013). "In contrast to deletion of STAT-1 or STAT-6, STAT-3 deletion in mice is lethal and therefore little is known about the role of STAT-3 in lung fibrosis." (PMID 20738867, 2010). "Additionally, biomimetic lipid nanocomplexes with STAT3 inhibitory peptides have shown promise in targeting lung fibrosis." (PMID 39859240, 2025). "Such interplay between ZEB1 and STAT3 may contribute to the pathogenesis of pulmonary fibrosis induced by COVID-1967,72." (PMID 40593827, 2025).